NRAS (NRAS proto-oncogene, GTPase)
Diseases named in the same sentence as NRAS in open-access papers (continued):
Sharing a sentence is not in itself a finding about the gene and the disease.
colorectal cancer (continued). "Molecularly defined groups of colorectal cancers such as microsatellite instability (MSI)-high tumors and cancers with alterations in the receptor tyrosine kinase/KRAS/BRAF pathways, such as KRAS/NRAS or BRAF mutations and ERBB2 amplifications, may benefit from targeted therapies." (PMID 39452477, 2024). "The presence of KRAS and NRAS mutations indicates a different mutation spectrum in the rectum, which might be more associated with sporadic colorectal cancers rather than hereditary syndromes such as Lynch." (PMID 39768914, 2024). "Mutations in the RAS gene family, encompassing KRAS, HRAS, and NRAS, represent a prevalent genetic alteration in colorectal carcinoma (CRC)." (PMID 38844562, 2024). "For example, National Comprehensive Cancer Network (NCCN) guidelines (version 2.2018) recommend KRAS, NRAS and BRAF mutation detection in metastatic colorectal carcinoma(CRC) for the well-established role in predicting therapeutic response." (PMID 35446881, 2022). "In 68 patients with colorectal carcinoma (CRC), key driver mutations were detected as follows: KRAS, 40 (59%); NRAS, 1 (1%); BRAF, 4 (6%); ERBB2, 2 (3%); and ERBB3, 1 (1%)." (PMID 35323313, 2022). "Recently, a phase I clinical study of lifirafenib (BGB-283), a RAF family kinase inhibitor, showed patients with KRAS-mutated endometrial cancer and NSCLC had a confirmed PR (n = 1 each), while no response was observed in patients with KRAS- or NRAS-mutated colorectal cancer (n = 20)." (PMID 34301278, 2021). "Moreover, dMMR, KRAS and NRAS mutation were not prognostic factors for stage I–III colorectal carcinoma." (PMID 29423347, 2018). "Our findings are in accord with an earlier landmark study showing that NRAS mainly signals through ERK to activate an anti-apoptotic phenotype, and suggesting that MEK1/2 inhibitors could be highly efficacious for patients with NRAS-mutant primary colorectal cancer." (PMID 27636997, 2016). "If one compares pediatric cancers to colorectal cancer which have an incidence of 400 cases per million in the USA, and a bias toward particular predictive biomarkers such as KRAS or NRAS mutation the feasibility of applying this technique to colorectal and other common cancers is clear." (PMID 25988159, 2014). "These included four colorectal cancer patients (two with KRAS G12V, one with KRAS Q61L, one with NRAS G61K; patients #18, #28, #79 and #21) and one non-small cell lung cancer patient with no targetable mutations (patient #29)." (PMID 39138315, 2024). "In colorectal cancer, ESMO suggests that an optimal gene panel should detect KRAS, NRAS, BRAF, NTRK, and ERBB2 amplification, although NGS is still only considered for research purposes." (PMID 38213074, 2024). "We assessed the clinicopathological features and prognostic values of KRAS, NRAS, BRAF, and DNA mismatch repair status in colorectal cancer (CRC) to provide real-world data in developing countries." (PMID 36862900, 2023). "Shi-r used a deep artificial neural network to predict the gene status of KRAS, NRAS, and BRAF in patients with liver metastasis of colorectal cancer." (PMID 38201314, 2023). "Colorectal cancer patients need to undergo KRAS, NRAS, BRAF, HER2 and microsatellite instability analysis." (PMID 34681592, 2021). "Here, we report that circPVT1 interferes with let-7 binding to NRAS, confirming this axis as one route by which circPVT1 can instigate an oncogenic program in A549 lung cancer cells and HCT116 colorectal cancer cells." (PMID 33907219, 2021). "Crucially, we were able to recapitulate our key findings on the circPVT1/let-7/NRAS axis in both A549 lung cancer cells and HCT116 colorectal cancer cells." (PMID 33907219, 2021). "Previous studies have also shown high concordance for blood and tissue alterations, such as those in the KRAS, NRAS, APC, and BRAF genes, in colorectal cancer." (PMID 32187847, 2020).
colorectal cancer (continued). "Over 24 months, 264 specimens from colorectal cancer (CRC) patients were brought to our laboratory for KRAS, NRAS, and BRAF characterization." (PMID 31036005, 2019). "In advanced clinical practice, the oncological management of colorectal cancer requires prior knowledge of KRAS, NRAS, and BRAF status, for the design of appropriate therapeutic strategies, with more gene mutations still surfacing as potential biomarkers." (PMID 31623125, 2019). "For example, in colorectal carcinomas Ras-MAPK pathway alteration are found in the majority of tumors, with a significant pattern of mutual exclusivity of alteration in KRAS, NRAS and BRAF12." (PMID 29118384, 2017). "We selected one hundred and twenty eight patients diagnosed with advanced colorectal cancer with a KRAS and NRAS unmutated tumor." (PMID 26824184, 2016). "For colorectal cancer (CRC) patients, international guidelines made RAS (KRAS and NRAS) status a prerequisite for the use of anti-epidermal growth factor receptor agents (anti-EGFR)." (PMID 27999270, 2016). "As with lung cancer, the most well-described driver alterations in colorectal cancer (for example, ‘hotspot alterations’ in KRAS, BRAF, NRAS and PIK3CA) are concordant between primary tumors and metastatic lesions." (PMID 25808843, 2015). "Most cancers with atypical KRAS mutations (291/335, 86.9%) had no additional mutations in BRAF, NRAS, or NF1, with the incidence of these mutations being far lower than the incidence of concomitant Ras mutations in atypical BRAF colorectal cancers." (PMID 39751654, 2025). "A total of 3795 patients were included in the analysis, of which 982 had colorectal cancer with 421 KRAS‐positive cases and 36 NRAS‐positive cases, 1246 had breast cancer with 410 PIK3CA‐positive cases, and 1567 had non‐small cell lung cancer with 300 EGFR‐positive cases." (PMID 40056420, 2025). "Of the 335 colorectal cancers, 13 (3.88%) with atypical KRAS also carried a typical KRAS mutation, and none of those tumors had an additional BRAF, NRAS, or NF1 mutation." (PMID 39751654, 2025). "In the context of colorectal cancer, this mechanism provides an alternative pathway for driving tumorigenesis in cases lacking canonical KRAS, NRAS, or BRAF mutations." (PMID 40868090, 2025). "The expression of SIGLEC9 was significantly elevated in colorectal cancer tissues, independent of mutations in the KRAS, NRAS, BRAF, PIK3CA, and AKT genes, as well as MSI status." (PMID 39727942, 2024). "In colorectal cancer, KRAS, NRAS, BRAF, and PIK3CA mutations induce a negative effect on the response to anti-EGFR therapies." (PMID 38248103, 2024). "Despite the high mutation frequencies of KRAS, NRAS, and BRAF in colorectal cancer (CRC), there are no effective and reliable inhibitors for these biomarkers." (PMID 37063257, 2023). "Further evaluation of the recommended molecular biomarkers for colorectal cancers, including more number of codon of KRAS, NRAS and BRAF, may also be required." (PMID 36083889, 2022). "Cetuximab is not indicated in EGFR expression colorectal cancer with a Ras‐mutant due to treatment‐related toxicity; EGFR amplification co‐occurred with an NRAS (p.G12S) mutation in a single tumor." (PMID 35229492, 2022). "The presence of KRAS/NRAS mutations suggests the lack of response to EGFR‐targeted therapies for patients with NSCLC, head and neck cancer or colorectal cancer." (PMID 34658138, 2021). "The present study characterized the functional consequences of non-canonical/novel KRAS and NRAS mutants identified in a targeted next-generation sequencing study of colorectal cancer specimens from Filipino patients." (PMID 31816869, 2019). "The non-canonical/novel KRAS and NRAS mutants were also assessed for their potential to resist apoptosis in colorectal cancer cells." (PMID 31816869, 2019).
colorectal cancer (continued). "A greater understanding of colorectal cancer biology followed by use of EGFR-targeted treatments has led to discovery of the importance of BRAF, PIK3CA, KRAS, and NRAS mutations in predicting a lack of response to EGFR-targeted therapy." (PMID 29254887, 2018). "However, EGFR remains a valid target in colorectal cancer within the population of patients wild-type for KRAS, NRAS, and BRAF, with proven clinical benefit." (PMID 29254887, 2018). "We further analyzed the association of EZH2 expression with the efficacy of anti-EGFR therapy in patients with colorectal cancer with no mutations in KRAS (codon 61/146), NRAS (codon 12/13/61), or BRAF (codon 600)." (PMID 28147317, 2017). "The use of anti-EGFR monoclonal antibodies (mAb anti-EGFRs) in colorectal cancer has shown that KRAS and NRAS represent the main resistance mechanisms to this type of treatment and are thus used in clinical practice to select the patients who should not be treated with anti-EGFR therapy." (PMID 27886225, 2016). "As one of the RAS family, NRAS shared close relations with KRAS, while unlike KRAS mutation occupies such a large percentage in colorectal cancer, NRAS mutations were rare." (PMID 24339949, 2013). "Retrospective analyses in the West suggest that mutations in KRAS codons 61 and 146, BRAF, NRAS, and PIK3CA are negative predictive factors for cetuximab treatment in colorectal cancer patients." (PMID 24006859, 2013). "Beyond DS-ALL, NRAS p.G13D has been recurrently described in RARA-negative acute promyelocytic-like leukemia with concomitant myelodysplastic syndrome, in lupus nephritis through aberrant RAS-MAPK signaling, in colorectal cancer, and in histiocytosis syndromes." (PMID 41020826, 2025). "Class 2–mutant and class 3–mutant colorectal cancers frequently co-occurred with additional Ras pathway mutations (29.0% and 45.7%, respectively, vs. 2.40% in class 1; P < 0.001), often at atypical sites (KRAS noncodon 12/13/61, NRAS, or NF1)." (PMID 39751654, 2025). "Whereas, different from other studies that NTRK gene rearrangements are highly enriched in RAS wild-type colorectal carcinomas, there were only two classical fusion cases harboring KRAS (n = 1) and NRAS (n = 1) mutations; but no BRAF mutation cases were in our study." (PMID 33996597, 2021). "In a large cohort of 85 patient-derived colorectal cancer xenografts, Bertotti and colleagues identified HER2 gene amplification in some xenografts, which were resistant to cetuximab and did not harbour mutations in KRAS, NRAS or BRAF genes." (PMID 31164152, 2019). "However, colorectal cancers harboring constitutive activating mutations in KRAS, NRAS and BRAF genes are not responsive to anti-EGFR therapy." (PMID 31711486, 2019). "Ion Torrent sequencing has been recently used to assess RAS status of colorectal carcinoma tumors in the CAPRI-GOIM clinical trial, and a panel of well-known predictive markers in the receptor tyrosine kinase pathway, including KRAS and NRAS, has been developed by the OncoNetwork Consortium." (PMID 26573425, 2016). "However, the preclinical and clinical performance of an NGS system for the detection of gene sets including minor mutations in KRAS, NRAS, and BRAF in patients with colorectal cancer has not been previously reported." (PMID 25954997, 2015). "Further, the presence of mutations in RAS family oncogenes is associated with a lack of response to targeted therapy: lung and colorectal carcinomas characterized by KRAS mutations and KRAS and NRAS mutations, respectively are unresponsive to treatment with anti-EGFR agents." (PMID 26435479, 2015). "We identified this complex in every PDX sample evaluated, including PDXs from lung, pancreatic and colorectal cancers with mutant KRAS, mutant HRAS or mutant NRAS and from the HBEC line as well as from the WI-38 nonimmortalized nontransformed human lung fibroblast line." (PMID 39528835, 2024).
cutaneous melanoma (217 papers, 2005 to 2026). A primary melanoma arising from atypical melanocytes in the skin. "Most cutaneous melanomas harbor activating mutations in BRAF or NRAS, but a distinct subset is defined by the oncogenic activation of KIT through somatic mutations." (PMID 41301010, 2025). "Genomic analyses have revealed that oncogenic mutations in genes such as BRAF and NRAS dominate the landscape of cutaneous melanoma, frequently initiating aberrant signaling pathways that foster unchecked cellular proliferation and survival." (PMID 40607411, 2025). "In the retrospective study aimed to explore the effects of BRAF and NRAS mutations on the effectiveness of ICIs in 1764 patients with advanced cutaneous melanoma." (PMID 39757723, 2025). "PARM exhibits a distinct molecular profile characterized by a notably low frequency of BRAF and NRAS driver mutations, occurring in less than 10% of cases compared to over 50% in cutaneous melanoma." (PMID 41458594, 2025). "Biologically, these tumors exhibit low mutational burden with scarce BRAF (3–11%) mutations but more frequent KIT (22%) and NRAS (5–14%) aberrations, contrasting with the UV-driven mutation profiles seen in cutaneous melanoma." (PMID 41002705, 2025). "It is important to acknowledge that direct activating mutations in KRAS are relatively infrequent in cutaneous melanoma (<5% in TCGA) compared to BRAF or NRAS mutations." (PMID 40607411, 2025). "BRAF and NRAS are mutant genes in skin cutaneous melanoma associated with different tumor immune microenvironments." (PMID 38438381, 2024). "Mucosal melanomas have a mutational profile characterized by KIT as the most frequent mutations (20–25% of cases), followed by BRAF and NRAS mutations (whose frequency is lower than that observed in cutaneous melanomas) and NF1 mutations." (PMID 39727691, 2024). "SK-MEL-147 cells harbor an NRAS mutation, which represents the second most frequent genetic mutation of cutaneous melanoma." (PMID 37259298, 2023). "Like in skin melanomas, NRAS and BRAF mutations are predominantly mutually exclusive in CMs, suggesting that the activating mutations in either of these two key molecules constitute the major oncogenic drivers through the MAPK (RAS/RAF/MEK/ERK) pathway." (PMID 37761808, 2023). "For example, among the top three exclusively mutated gene pairs are BRAF and NRAS in skin cutaneous melanoma (p = 1.1 × 10–44), KIT and PDGFRA in gastrointestinal stromal tumour (p = 3.3 × 10–37), and EGFR and KRAS in lung adenocarcinoma (p = 6.6 × 10–29)." (PMID 37550388, 2023). "The combination of Omipalisib and MEK inhibitors significantly reduced tumor size in vivo in xenograft tumor models and was synergistic in vitro in NRAS-mutated skin melanoma cell lines." (PMID 35326726, 2022). "In ultraviolet-shielded melanoma, mutations of BRAF, NRAS or NF1 are less frequent compared to cutaneous melanoma, but the existence of other cancer driver gene mutations are detected." (PMID 35688842, 2022). "Clinically and histologically, conjunctival melanomas, which harbour mutations in BRAF and NRAS, show greater similarity to cutaneous melanoma than does UM." (PMID 35682684, 2022). "Two cases (8.0%) had mutations in NRAS of p.Q61R and p.G12D, which were consistent with hot spots in cutaneous melanoma." (PMID 35688842, 2022). "In mucosal melanoma, mutations in BRAF (12.0%) and NRAS (8.0%) were both lower than that in western population, and lower than Chinese cutaneous melanoma." (PMID 35688842, 2022). "The 7 cases of NRAS mutations were targeted to hotspots on codon 61 and codon 12, which were hot spot mutations of cutaneous melanoma." (PMID 35688842, 2022). "NRAS is mutated in ∼30% of cutaneous melanomas, mostly at the Q61 residue in the switch II region that abolishes RAS GTPase activity and, thus, results in constitutive activation." (PMID 35234863, 2022).
cutaneous melanoma (continued). "NRAS mutations were seen in 19.6% of primary nodular subtype of cutaneous melanoma cases in Yogyakarta and Central Java Province, Indonesia, which is consistent with data worldwide." (PMID 34110110, 2022). "Uveal melanoma has radically different genetic causes compared to cutaneous melanoma because mutations in BRAF or NRAS are exceedingly rare." (PMID 35234863, 2022). "Twelve (43%) NRAS mutation bearing cutaneous melanoma cases had additional mutations, with two harboring Tier 1 NRAS mutations that cannot be identified by the Idylla system." (PMID 35627184, 2022). "Our results are in line with previous data in NRAS-mutated skin melanoma cell lines where Omipalisib was the most potent inhibitor of the PI3K/mTOR pathway." (PMID 35326726, 2022). "The incidence of BRAF mutation is 35-50% in cutaneous melanoma, while the upstream NRAS mutation frequency is 15-20%." (PMID 34290710, 2021). "For the majority of cases, NRAS mutations are missense mutations of codons 12, 13, and 61, all of which influence GTPase activity; however, mutations to codon 61 alone account for up to 80% of NRAS mutations in cutaneous melanoma disease." (PMID 34155457, 2021). "According to the literatures, KRAS mutations are common in pancreas, colon and lung cancers, whereas NRAS mutations are common in myeloid leukemias and cutaneous melanomas." (PMID 34102999, 2021). "NRAS mutations are described in 27% of cutaneous melanoma, with a Q61K mutation as the most common mutation followed by Q61R." (PMID 34071371, 2021). "NRAS mutations occur in more than 20% of patients with cutaneous melanoma, leading to the activation of MAPK, PI3K, and other cellular signaling pathways, and resulting in cell growth, proliferation, and cell cycle dysfunction." (PMID 34035810, 2021). "Cutaneous melanoma is a particularly suitable model since BRAF or NRAS hotspot mutations are found in 60% to 70% of patients and are already routinely investigated for any metastatic cutaneous melanoma." (PMID 33920470, 2021). "Among the patients with NRAS mutation receiving immunotherapy, the only two responsive patients were both in the cutaneous melanoma group (9.5%)." (PMID 34290710, 2021). "V-raf murine sarcoma viral oncogene homolog B (BRAF) and neuroblastoma RAS viral oncogene homolog (NRAS) mutations are different in mucosal melanomas in comparison to cutaneous melanomas." (PMID 34571863, 2021). "Only one study compared primary cutaneous melanoma and corresponding metastases and showed the detection of emerging NRAS mutations in two patients." (PMID 34072863, 2021). "The incidences of NRAS mutations in acral, mucosal, and cutaneous melanoma were 9.0%, 13.0%, and 10.8% respectively." (PMID 34290710, 2021). "The presence of NRAS mutations correlated with worse OS in a series of 2793 cutaneous melanomas by Bai and colleagues." (PMID 34571863, 2021). "Pimasertib has shown clinical activity in patients with NRAS-mutated cutaneous melanoma and a safety profile that is consistent with the known toxicities of MEK inhibitors." (PMID 32610581, 2020). "The major driver of skin melanoma is the mutant BRAF in almost half of the cases followed by NRAS mutation as the second most frequent one." (PMID 31848942, 2020). "NRAS mutations are the most common alterations among RAS isoforms in cutaneous melanoma, with patients harboring these aggressive tumors having a poor prognosis and low survival rate." (PMID 31549767, 2020). "On the basis of exome and genome sequencing studies, BRAF and NRAS were identified as the most commonly mutated genes in cutaneous melanoma patients." (PMID 31549767, 2020). "In conclusion Pimasertib has shown clinical activity in patients with NRAS-mutated cutaneous melanoma and a safety profile that is consistent with the known toxicities of MEK inhibitors." (PMID 32610581, 2020).